APOBR (apolipoprotein B receptor)
Description:
Macrophage receptor that binds to the apolipoprotein B48 (APOB) of dietary triglyceride (TG)-rich lipoproteins (TRL) or to a like domain of APOB in hypertriglyceridemic very low density lipoprotein (HTG-VLDL). Binds and internalizes TRL when out of the context of the macrophage. May provide essential lipids to reticuloendothelial cells. Could also be involved in foam cell formation with elevated TRL and remnant lipoprotein (RLP). Mediates the rapid high-affinity uptake of chylomicrons (CM), HTG-VLDL, and trypsinized (tryp) VLDL devoid of APOE in vitro in macrophages.
Synonyms: APOB48R; APOB100R
Tractability: Antibody: UniProt places it where antibodies can reach, with high confidence; its Gene Ontology location is reachable by antibodies, with high confidence; the Human Protein Atlas places it where antibodies can reach. PROTAC: ubiquitination databases record sites on it; its protein half-life has been measured.
Gene: Protein-coding gene on chromosome 16 (28,494,639 to 28,498,964, forward strand). Ensembl gene ENSG00000184730.
Subcellular location: Cell membrane
Subcellular location (Human Protein Atlas): Plasma membrane; Centrosome
Pathways (Reactome):
Transport of small molecules: VLDL clearance
Gene Ontology:
Molecular function: lipoprotein particle receptor activity; very-low-density lipoprotein particle receptor activity
Biological process: foam cell differentiation; triglyceride metabolic process; lipid transport; vesicle-mediated transport
Cellular component: membrane; plasma membrane
Genetic constraint (gnomAD): Loss-of-function variants: 57 observed, 71.78 expected, observed/expected ratio (o/e) 0.79, 90% interval 0.64 to 0.99. The upper end of that interval is the gene's LOEUF score, 0.99, which puts it in group 4 of 6, group 1 being the genes least tolerant of losing a copy. Missense variants: 1,438 observed, 1,274.1 expected, observed/expected ratio (o/e) 1.13, 90% interval 1.08 to 1.18. Synonymous variants: 587 observed, 524.05 expected, observed/expected ratio (o/e) 1.12, 90% interval 1.05 to 1.2.
Homologues: Orthologues: macaque APOBR (86% identical), dog APOBR (56% identical), rat Apobr (42% identical), mouse Apobr (42% identical).
Diseases named in the same sentence as APOBR in open-access papers:
APOBR is named in the same sentence as 14 diseases in open-access papers, as found by Europe PMC text mining. Sharing a sentence is not in itself a finding about the gene and the disease. The quoted sentences say what the papers report.
Obesity (6 papers, 2015 to 2024). Accumulation of substantial excess body fat. "Few associations have been identified for APOBR, e.g., DNA methylation locus for obesity, GWAS loci for allergy and pneumonia, and transcript upregulation in Streptococcus pneumoniae infection (pneumonia, keratitis, and sepsis)." (PMID 39457448, 2024). "Variants in APOBR contributed as strongly as variants in SH2B1 to the association with extreme obesity in the chromosomal region chr16p11.2." (PMID 25955518, 2015). "Two polymorphisms rs180743 (APOBR p.Pro428Ala) and rs3833080 (APOBR p.Gly369_Asp370del9) showed nominal association to (extreme) obesity (uncorrected p = 0.003 and p = 0.002, respectively)." (PMID 25955518, 2015). "In order to fine map the chromosomal region chr16p11.2 for further obesity associated variants, we screened the coding regions of APOBR, SULT1A1, SULT1A2, and TUFM for variants in 95 extremely obese children and adolescents." (PMID 25955518, 2015). "In sum, of the five analyzed genes SH2B1 and APOBR comprised non-synonymous variants associated with obesity." (PMID 25955518, 2015). "The Chr16p11 gene set consists of 212 genes, some of which are associated with obesity, including SH2B1, APOBR, SULT1A1, SULT1A2, and TUFM." (PMID 29854750, 2018). "This miRNA has not been previously reported as associated with obesity, however among its targets are those involved in the pathogenesis of obesity-related complications, e.g., genes encoding interleukins (IL-6, IL-17B and IL-22), apolipoproteins (APOA5) and their receptors (APOBR)." (PMID 29280944, 2017).
pneumonia (2 papers, 2018 to 2024). An acute, acute and chronic, or chronic inflammation focally or diffusely affecting the lung parenchyma, caused by an infection in one or both of the lungs (by bacteria, viruses, fungi, or mycoplasma.). "The direct molecular link existing between APOB and APOBR is very suggestive of an association of pneumonia caused by S. pneumoniae and the APOB pathway." (PMID 29751582, 2018). "By analyzing various transcriptomic data repositories, we found strong supportive evidence for the role of MEIS1, TSPAN15 and APOBR (encoding the receptor of the APOB protein) in pneumonia in mouse and human models." (PMID 29751582, 2018).
diabetes (1 paper, 2024). "Loci for the other genes—PTP4A1, APOBR, BMS1P4-AGAP5, MAPK8IP1P1, GYS2, FAM25C, and GK5–were formerly associated with traits involved with comorbidities of OSA, i.e., BMI, weight, triglycerides, blood pressure, stroke, brain volume, cortical thickness, mood, insulin, and diabetes." (PMID 39457448, 2024).
liver cancer (1 paper, 2025). An epithelial or non-epithelial malignant neoplasm that arises from the liver. "Antigenicity, molecular weight, subcellular localization and expression site predictions were used to shortlist liver cancer associated proteins including AMBP, CFB, CDHR5, VTN, APOBR, AFP, SERPINA1 and APOE." (PMID 39752339, 2025).
Type 1 diabetes (1 paper, 2025). "We show colocalization of pQTLs for CTRB1, APOBR, IL7R, CPA1, and PNLIPRP1 with Type 1 diabetes GWAS signals, and Mendelian randomization causally implicates each of these five proteins in the aetiology of Type 1 diabetes." (PMID 40263317, 2025).
APOBR also shares sentences with these, for which no sentence is quoted: Allergy (1 paper); COVID-19 (1); endothelial dysfunction (1); hypercholesterolaemia (1); Hypertension (1); keratitis (1); Sepsis (1); Streptococcus pneumoniae infection (1); Stroke (1).